RNU1-93P (RNA, U1 small nuclear 93, pseudogene)
Synonyms: HTR2B; TSARG1
Gene: Small nuclear RNA gene on chromosome 2 (231,133,462 to 231,133,630, forward strand). Ensembl gene ENSG00000201574.
Homologues: Orthologues: chimpanzee U1 (99% identical), macaque U1 (93% identical). Paralogues in human: RNU1-1 (74% identical), RNU1-2 (74% identical), RNU1-27P (74% identical), RNU1-28P (74% identical), RNU1-3 (74% identical), RNU1-4 (74% identical), RNU1-83P (74% identical), RNVU1-18 (74% identical), RNVU1-29 (74% identical), RNVU1-31 (74% identical), U1 (74% identical), RNVU1-28 (73% identical), and 134 more.